EDN1 (endothelin 1)
Diseases named in the same sentence as EDN1 in open-access papers (continued):
Sharing a sentence is not in itself a finding about the gene and the disease.
Obesity (continued). "Not all studies agree on the finding of an increase in plasma endothelin-1 levels in hypertensive children and adolescents; in addition, the picture is often confused by the concomitant presence of obesity, a condition that stimulates the production of endothelin-1." (PMID 34085102, 2022). "On the one hand, in obesity, the insulin-mediated activation of the PI 3-kinase pathway is impaired, whereas the activation of the extracellular signal-regulated protein kinase 1/2 and the production of endothelin-1 by insulin are normal." (PMID 35805693, 2022). "A study in Mexico City demonstrated possible mechanisms in children associated with the development of obesity that included differences between exposed and non-exposed children in leptin, endothelin-1, glucagon-like peptide-1 (GLP 1), ghrelin, and glucagon." (PMID 33652701, 2021). "To explore the significant interactions identified above, we estimated the adjusted mean ratio in carotid IMT measurements for either EDNRA or EDN1 minor—major/minor—minor genotypes in comparison with the major—major genotype stratified by gender, regular exercise, and obesity." (PMID 26040574, 2015). "However, in obesity, dysfunctional and inflamed adipose tissue secretes proinflammatory adipokines that impair normal vasoactivity, resulting in an imbalance in constrictors and dilators, including endothelin-1 and nitric oxide, respectively." (PMID 36766750, 2023). "Indeed, the levels of endothelin-1 increase in obesity and type II diabetes." (PMID 23573411, 2013). "More recently, we were able to analyse the cross-talk between obesity, angiotensin II (Ang II), NOX2 and endothelin-1 (ET-1) in more detail." (PMID 37627585, 2023). "We found gender, regular exercise, and obesity significantly interacted with SNPs in the EDNRA gene, and gender interacted with SNPs in the EDN1 gene to influence carotid IMTs in the Han Chinese participants of the TCHS study." (PMID 26040574, 2015). "The gene-gender, gene-exercise, and gene-obesity interactions for EDNRA and EDN1 SNPs on carotid IMT were explored." (PMID 26040574, 2015). "Therefore, in our study we examined the associations of five SNPs in EDN1 and EDNRA genes with carotid IMT in a Han Chinese sample from the Taichung Community Health Study (TCHS), and evaluated their interaction effects by gender, regular exercise, and obesity status." (PMID 26040574, 2015). "Similar to changes typically present in animal models of obesity and obese humans, the GPER0 obesity model is characterized by visceral obesity, dyslipidemia, insulin resistance as well as enhanced responses to endothelium-derived vasoconstrictor prostanoids and to endothelin-1." (PMID 24244459, 2013).
Hyperglycemia (76 papers, 2005 to 2025). An increased concentration of glucose in the blood. "For example, in retinal arteriolar smooth muscle cells, hyperglycaemia and hypoxia can cause endothelin-1 resistance and inhibit Ca2+ influx channels." (PMID 32385602, 2020). "As mentioned, hyperglycaemia enhances the secretion of vasoconstricting factor, endothelin-1 (ET-1), and decreases NO production in the aorta of diabetic rats and coronary microvessels in humans." (PMID 40650241, 2025). "Hyperglycemia-related superoxides, vasoconstrictive endothelin-1, and matrix metalloproteinases contribute to vascular myogenic responses and remodeling." (PMID 40567422, 2025). "Its expression is activated by pro-inflammatory cytokines, endothelin-1 (ET-1), reactive oxygen species, oxLDLs, hyperglycemia, and shear stress." (PMID 39859253, 2025). "This study aims to find out how hyperglycemia affect oxidative stress and then the expression and methylation of endothelin 1 (ET-1) gene in in human umbilical vein endothelial cells (HUVEC)." (PMID 37139232, 2023). "Hypertriglyceridemia and hyperglycemia following fat consumption have been shown to stimulate the vasoconstrictor endothelin-1 (ET-1), reactive oxygen species (ROS) and inflammatory markers, which subsequently reduce endothelium-derived NO." (PMID 38024378, 2023). "Hyperglycemia affects the bioavailability of nitric oxide and increases the number of oxygen radicals and endothelium-derived vasoconstrictors such as endothelin-1, prostanoids, and angiotensin II." (PMID 34124101, 2021). "Hyperglycemia inhibits production of vasodilators like nitric oxide, and increases vasoconstrictors like endothelin-1." (PMID 31638908, 2019). "Features of DN include hyperglycemia, inflammation, reactiveoxygen species (ROS) production, and endothelin-1 (ET-1) and renin-angiotensinsystem (RAS) activation." (PMID 31508666, 2019). "The inhibition of endogenous synthesis of NO and the elevation of vascular remodeling accelerators such as angiotensin II and endothelin-1 were considered as adverse factors in hyperglycemia." (PMID 29692859, 2018). "AQP1 overexpression in ECs suppressed hyperglycemia-induced cellular hypoxia, endothelin-1 and fibronectin overproduction, and apoptosis." (PMID 27383386, 2016). "As endothelin-1 and fibronectin overproduction and apoptosis are characteristic features in both hyperglycemia and hypoxia, we evaluated the effect of AQP1 overexpression on these phenomena." (PMID 27383386, 2016). "Hyperglycemia-induced vascular deleterious effects are partially mediated by the endothelin-1 (ET-1)." (PMID 24376792, 2013). "Other factors that have recently been reported to induce PSC activation (as assessed by proliferation, migration, collagen production, αSMA expression or cytokine expression) include hyperglycaemia, endothelin 1, COX-2, galectin 1 and fibrinogen." (PMID 22973234, 2012). "Regarding triggered factors in tissues, elevated pro-inflammatory cytokines, an excess of endothelin-1, hyperglycemia, hypercholesterolemia and disturbance of Ca2+ homeostasis are active in initiating ER stress." (PMID 22226148, 2012). "Enhanced endothelin-1 activity has been associated with decreased retinal blood flow in diabetic animals, and hyperglycemia may increase retinal endothelin-1 secretion." (PMID 40926896, 2025). "The recognized complex mechanisms by which hyperglycemia modifies endothelial function include reduction in nitric oxide (NO) bioavailability, production of vasoconstrictors such as endothelin-1 (ET-1), increased generation of reactive oxygen species (ROS), and glycation of proteins and lipids." (PMID 34299486, 2021). "In that context, it is known that postprandial hyperglycemia induces oxidative stress, triggering atherogenic alterations, like secretion of pro-inflammatory cytokines, adhesion molecules, or vasoconstrictive substances (e.g., endothelin-1)." (PMID 31947853, 2020).
Hyperglycemia (continued). "Indeed, there are some common aspects between hyperglycemia and hypoxia-induced phenomena, such as overproduction of endothelin-1 and fibronectin, and induction of apoptosis." (PMID 27383386, 2016). "Additionally, hyperglycemia-induced activation of nuclear factor-κ (NF-κ) B increases the levels of endothelin-1 (ET-1), vascular cell adhesion molecule- (VCAM-) 1, intercellular adhesion molecule- (ICAM-) 1, IL-6, and tumor necrosis factor- (TNF-) α." (PMID 26881236, 2016). "Moreover, hyperglycemia itself increases the release of the vasoconstricting peptide endothelin-1 from cultured endothelial cells, offsetting the vasodilating actions of NO." (PMID 25785277, 2015). "In the same research study, it is confirmed that hyperglycemia induced miR-200b downregulation, resulting in increased expression of the transcriptional coactivator p300, through which the levels of vasoactive factors Endothelin-1 (ET-1) and VEGF are increased." (PMID 41010004, 2025). "The upregulation of PKC (β and γ) triggered by hyperglycemia significantly impacts endothelial cells, increasing their permeability, reducing nitric oxide production, and increasing synthesis of vasoconstrictors like endothelin 1 (ET-1) and thromboxane A2 (TxA2)." (PMID 38132873, 2023). "Hyperglycemia results in the impairment of endothelial cells, reducing the generation of the vasodilator NO, thus favoring a vasoconstrictive state through the increase in vasoconstrictors and pro-thrombotic mediators, endothelin-1 (ET-1) and thromboxane A2 (TXA2)." (PMID 36299902, 2022). "However, it is important to note that AQP1 may serve as a molecular target to prevent diabetic complications because hyperglycemia-induced endothelin-1 and fibronectin overproduction and apoptosis were all suppressed by overexpression of AQP1." (PMID 27383386, 2016). "Hyperglycaemia, as shown in T2DM, also results in the upregulation of endothelin 1 (ET-1) while reducing nitric oxide (NO) secretion, thus creating an imbalance between endothelial vasoconstrictors and vasodilators." (PMID 38024366, 2023). "Also, diabetes is correlated with the superabundant production of reactive oxygen species (ROS) by hyperglycemia, which contributes to the elimination of endothelium-derived relaxing factor nitric oxide (NO) and the accumulation of endogenous vasoconstrictor substances, such as endothelin-1." (PMID 29692859, 2018). "Therefore, hyperglycaemia, hyperlipidemia and proinflammatory cytokines are known to selectively impair the phosphoinositide 3-kinase (PI3K)/AKT/ endothelial nitric oxide synthase (eNOS) pathway, increase oxidative stress and enhance the release of endothelin 1 (ET-1) from the endothelium." (PMID 36142173, 2022). "Several endocrine and local stimuli such as hyperglycemia, elevated plasma levels of NEFA (non-esterified free acids), lipoproteins, oxidative stress, angiotensin-II, endothelin-1, and cytokine themselves have been shown to induce proinflammatory cytokine production by activating NF-κB pathway." (PMID 33171670, 2020).
coronary artery disease (65 papers, 2007 to 2026). "Endothelin-1 (ET-1) is an endothelial peptide crucial for physiological regulation of vasomotor tone and implicated in the pathogenesis of various coronary artery disorders." (PMID 36262459, 2022). "This is the first report of genetic polymorphisms in the EDN-1 gene linked to an associated risk for disease in a cohort of 525 coronary artery disease patients and 675 control subjects." (PMID 33126567, 2020). "Nonetheless, the role of ET-1 (EDN1) gene variants on coronary artery disease (CAD) risk remains poorly understood." (PMID 29654172, 2018). "Impact of endothelin-1 Lys 198Asn polymorphism on coronary artery disease and endrogan damage in hypertensives." (PMID 23401650, 2013). "Both plasma levels of the precursor big endothelin-1 and tissue levels of ET-1 are correlated with the severity of coronary artery disease." (PMID 41153763, 2025). "The rs9349379 SNP of the PHACTR1 locus (6p24), which is associated with coronary artery disease (CAD), migraine headache, cervical artery dissection, fibromuscular dysplasia, and systemic arterial hypertension, is a regulator of endothelin-1 expression." (PMID 35625487, 2022). "Endothelin-1 is a potent vasoconstrictor that has a known regulatory role in vascular vasomotor tone in coronary artery disease." (PMID 32154019, 2019). "The endothelin-1 (ET-1) peptide is an important participant in the pathophysiology of coronary artery disease and myocardial infarction." (PMID 28323857, 2017). "Circulating endothelin-1 levels have been shown to increase in patients with advanced atherosclerosis and coronary artery disease progression." (PMID 26573599, 2015). "Endothelin-1 is known to have a regulatory role in coronary vascular resistance and myocardial capillary blood flow in coronary artery diseases." (PMID 25186061, 2014). "Patients with ischemic heart disease have elevated plasma levels of endothelin-1 and angiotensin II and show increased vascular tone." (PMID 19706169, 2009). "The role of endothelialdysfunction in developing cardiovascular pathology in COPD patients was studied.A relationship was found between the concentration of the marker of endothelialdysfunction endothelin-1 and the presence of coronary artery disease in COPDpatients." (PMID 39077394, 2023). "In the conducted studies among patients with coronary artery disease, it was shown that blocking the A-type receptor for endothelin-1 improved the function of the vascular endothelium by inhibiting the vasoconstrictor effect of ET-1." (PMID 35742539, 2022). "In this context, the current study aims to analyze whether certain inflammatory markers, i.e., interleukin 6 (IL-6) and endothelin 1 (ET-1), can play a role in the diagnosis of ischemic heart disease through microvascular involvement in women." (PMID 34683106, 2021). "Endothelin 1 (ET-1) has been shown to have a key role in homeostasis and function of endothelium and maybe fundamental in the relationship between coronary heart disease (CHD) and periodontitis." (PMID 32015361, 2020). "Our aim was to investigate whether circulating endothelin-1 levels predict coronary heart disease (CHD) in Sweden." (PMID 26573599, 2015). "Danshen injection combined with clopidogrel can improve clinical efficacy in the treatment of coronary heart disease; regulate the levels of NO, thromboxane B2 (TXB2), and endothelin-1 (ET-1); promote endothelial function recovery; and have better therapeutic effects than using clopidogrel alone." (PMID 39684932, 2024). "Edn1 also defined as a critical gene in non-obstructive coronary artery disease." (PMID 39863867, 2025).
ovarian carcinoma (64 papers, 2003 to 2026). A malignant neoplasm originating from the surface ovarian epithelium. "In ovarian cancer cells, βArr1 is linked with the endothelin-1-induced activation of Akt, GSK-3β in integrin-linked kinase (ILK) activation." (PMID 23418490, 2013). "The co-treatment of cisplatin with curcumin induced apoptosis by activating NRF2 and inhibited ovarian cancer plasticity marker endothelin-1 (ET-1) in SKOV3 cells as well as in a rat model." (PMID 39416904, 2024). "Transcriptional activation of EDN1 by β-catenin has been also observed in colon, prostate, and ovarian cancer and creates a self-amplifying positive-feedback loop that forms an ET-1 autocrine circuit." (PMID 38072958, 2023). "Endothelin-1 (ET-1) axis plays the most critical role in the epithelial plasticity in ovarian cancer." (PMID 35517894, 2022). "In epithelial ovarian cancer, Endothelin-1 (EDN-1) was found to regulate the epithelial–mesenchymal transition (EMT) and a chemoresistant phenotype." (PMID 35887024, 2022). "The activation of the ETAR by endothelin-1 (ET-1) is a key factor in the development of ovarian cancer by promoting anti-apoptosis, invasion, and neoangiogenesis." (PMID 34943797, 2021). "Endothelin-1 (ET-1), is a powerful mitogenic peptide produced by different tumors including ovarian cancer." (PMID 27258020, 2016). "In ovarian cancer the activation of the endothelin-A receptor (ETAR) by endothelin-1 (ET-1) plays a central role in ovarian cancer progression." (PMID 27529230, 2016). "In contrast, EDN1 (endothelin 1), which is a known pro-survival protein in ovarian carcinoma, was more strongly induced in resistant cells, in line with a pro-survival response." (PMID 26573568, 2015). "EDN1 is a growth-promoting peptide that stimulates the proliferation of many malignant cells, such as melanoma, hepatoma, prostate, colorectal, and ovarian cancer cells." (PMID 24416389, 2014). "For instance, it has been demonstrated that the endothelin-1/ endothelin A receptor (ET-1/ETAR) axis in epithelial ovarian cancer (EOC) cells induces vascular-endothelial growth factor (VEGF) expression through HIF-1α nuclear accumulation, resulting in the invasion of cancer cells." (PMID 29482638, 2018). "Moreover, comparing with the normal control samples, EDN1 mRNA expression was increased in inflammatory breast cancer, nasopharyngeal carcinoma, metastatic prostate cancer, gastric cancer, papillary thyroid cancer, and ovarian cancer epithelial cells." (PMID 24416389, 2014). "The prognostic role of COL1A1, FN1, EDN1 (ET-1) and ARRB1 (β-arr1) gene expression was evaluated using the Kaplan–Meier plotter database and clinical ovarian cancer tissue samples." (PMID 39985042, 2025). "EDN1 exhibited context-dependent dysregulation, with significant upregulation in 9 cancers (including CRC, gastric, and ovarian cancers) and downregulation in 9 others (e.g., breast, prostate)." (PMID 41425720, 2025). "The binding of β-arrestin 1 to the endothelin-1 (ET-1)/ET A-type receptor (ETAR) signaling complex, and the activation of β-catenin promote the migration, invasion, and progression of ovarian cancer cells." (PMID 36969037, 2023). "The ovarian cancer cell lines, PEO4 and PEO14, not only express ET-1 (endothelin 1) and ET-3 (endothelin 3) but also ETAR and ETBR, which suggests that ovarian cancer cells stimulate the ETR pathway in an autocrine fashion." (PMID 28439256, 2017). "Among these, the endothelin-1 (ET-1) receptors (ET-1R), ETA receptor (ETAR), and ETB receptor (ETBR), exert critical functions in many tumor settings and their aberrant expression has been observed in several malignances including ovarian cancer (OC)." (PMID 31551935, 2019). "Factors such as endothelin A receptor/endothelin-1 axis, autocrine BMP4 signaling pathway, and 17ß-estradiol have been reported to trigger EMT and promote tumor progression by up-regulating Snail1 activity in human ovarian cancer cells." (PMID 21559368, 2011).